EEF1AKMT4 (EEF1A lysine methyltransferase 4)
Description:
Protein-lysine methyltransferase that efficiently catalyzes three successive methylations on 'Lys-36' in eukaryotic translation elongation factor 1 alpha (EEF1A1 or EEF1A2).
Tractability: Small molecule: a structure with a bound ligand is known. PROTAC: ubiquitination databases record sites on it.
Gene: Protein-coding gene on chromosome 3 (184,249,609 to 184,258,759, forward strand). Ensembl gene ENSG00000284753.
Subcellular location (Human Protein Atlas): Cytosol; Nucleoplasm
Gene Ontology:
Molecular function: methyltransferase activity; protein-lysine N-methyltransferase activity; S-adenosylmethionine-dependent methyltransferase activity
Genetic constraint (gnomAD): Loss-of-function variants: 17 observed, 24.4 expected, observed/expected ratio (o/e) 0.7, 90% interval 0.48 to 1.04. The upper end of that interval is the gene's LOEUF score, 1.04, which puts it in group 4 of 6, group 1 being the genes least tolerant of losing a copy. Missense variants: 318 observed, 348.94 expected, observed/expected ratio (o/e) 0.91, 90% interval 0.83 to 1. Synonymous variants: 140 observed, 149.91 expected, observed/expected ratio (o/e) 0.93, 90% interval 0.81 to 1.08.
Homologues: Orthologues: rabbit EEF1AKMT4 (92% identical), pig EEF1AKMT4 (88% identical), dog EEF1AKMT4 (87% identical), mouse Eef1akmt4 (84% identical), rat Eef1akmt4 (84% identical), zebrafish ece2a (48% identical), tropical clawed frog EEF1AKMT4 (47% identical), Caenorhabditis elegans C17E4.11 (27% identical). Paralogues in human: METTL13 (32% identical), CSKMT (21% identical).
Diseases named in the same sentence as EEF1AKMT4 in open-access papers:
EEF1AKMT4 is named in the same sentence as 1 disease in open-access papers, as found by Europe PMC text mining. Sharing a sentence is not in itself a finding about the gene and the disease. The quoted sentences say what the papers report.
tumor (1 paper, 2025). "In conclusion, the evolutionarily conserved EEF1AKMT4-eEF1A2K36me3-ribosome protein synthesis-tumor promoting signals axis acts as a mechanism that promotes GBC progression and may be a potential therapeutic target for GBC lymph node metastasis." (PMID 41705259, 2025). "EEF1AKMT4 trimethylates eEF1A2 at K36 site in GBC and is essential for the tumor-promoting effect of eEF1A2." (PMID 41705259, 2025).